CD2AP (CD2 associated protein)
Diseases named in the same sentence as CD2AP in open-access papers (continued):
Sharing a sentence is not in itself a finding about the gene and the disease.
gastric cancer (8 papers, 2016 to 2025). A primary or metastatic malignant neoplasm involving the stomach. "Later, it was found that CD2AP also plays a regulatory role in epithelial cell junction formation, and it was also linked to gastric cancer development as it can inhibit metastasis by promoting cellular adhesion and cytoskeleton assembly." (PMID 37894817, 2023). "Although it has already been reported that TKS4 regulates colon cancer cell migration and plays a role in an EMT-like process, CD2AP has also been connected to cancer development and the inhibition of metastasis in gastric cancer (although the underlying mechanisms remain elusive)." (PMID 37894817, 2023). "In the present study, CD2AP was positively correlated with longer OS, which was consistent with the effect in gastric cancer." (PMID 38694875, 2024). "CD2AP has been reported to inhibit tumor metastasis by promoting cell adhesion and cytoskeleton assembly in gastric cancer." (PMID 38694875, 2024). "However, another study proved that CD2AP inhibited tumour metastasis and played an anti-tumour role in gastric cancer." (PMID 41425578, 2025). "Another study showed that CD2AP expression was decreased in diffuse gastric cancer and CD2AP could inhibit gastric cancer metastasis by promoting cellular adhesion and cytoskeleton assembly." (PMID 39353894, 2024). "The CD2AP was able to inhibit the metastasis of gastric cancer." (PMID 36311703, 2022). "To determine whether NKX6.3 reduces gastric cancer cell migration through down-regulation of the Rho-GTPase family, we examined the expression of CD2-associated protein (CD2AP), RhoA, Cdc42, p-Rac1/Cdc42 and Rac1/2/3 proteins, in AGSNKX6.3 and MKN1NKX6.3 cells." (PMID 27333045, 2016). "However, no study has investigated the expression and biological significance of CD2AP in gastric cancer (GC) to date." (PMID 31989722, 2020). "Because it was reported that CD2AP bound CAPZA1 to promote intercellular adhesion and to influence cell cytoskeleton in gastric cancer, there is a possibility that CD2AP also interacts with certain protein(s) in the NF-kB signaling to regulate the NF-kB activity." (PMID 39353894, 2024).
viral infection (7 papers, 2018 to 2024). "These circRNAs were annotated to 21 parental genes, of which seven had functions relating to immune response or virus infection, such as CD2AP, QKI, and AKIRIN2." (PMID 35049781, 2022). "Among the proteins with an undescribed role in virus infection, CD2AP was one of the most prominent, at least when judged by its relative abundance in our CHIKV and VEEV nsP3 HVD interactors dataset." (PMID 29702546, 2018). "Our results thus suggest that CD2AP can be a specific target to enhance antiviral protective immunity during viral infection or vaccination." (PMID 29734372, 2018). "This study demonstrated that deletion of CD2AP in T cells results in skewing of CD4 T cell differentiation towards TFH cells in response to viral infection, leading to enhanced control of LCMV that requires GC-derived high affinity antibody responses." (PMID 29734372, 2018). "The development of small molecules that inhibit the function of CD2AP in the context of viral infection or in the context of vaccines, could enhance the antibody response." (PMID 29734372, 2018). "Our data demonstrated that TFH differentiation was enhanced by Cd2ap-deficiency specifically in viral infection, but not in immunization with SRBCs or NP-CGG in alum." (PMID 29734372, 2018). "Thus, the nsP3:CD2AP interaction is also efficiently formed in the context of virus infection." (PMID 29702546, 2018). "CD2AP inactivation promotes CD4 T-cell differentiation towards the follicular helper lineage, leading to enhanced control of viral infection by augmented germinal center response in chronic LCMV infection." (PMID 37962454, 2024). "CD2AP expressed on the surface of CD4+ T cells regulates follicular helper T cell differentiation and enhances antibody responses during viral infection." (PMID 37949890, 2023). "pDC cells produce large amounts of IFNs in response to viral infection. pDC-specific markers CLEC4C (also known as BDCA-2), IL-3Rα (CD123), and CD2AP were highly expressed after MSC treatment." (PMID 34702946, 2021).
colon cancer (6 papers, 2010 to 2025). "Furthermore, our research group identified CD2-associated protein (CD2AP) as a protein-protein interaction partner of Tks4 in colon cancer cells." (PMID 39234565, 2024). "We entered the analyzed colon cancer marker gene set (CD2AP, GRB2, WASL, SRC, CTTN, CAPZA1, and Tks4) into this tool to elucidate which cancer hallmark-related pathways are influenced by these proteins." (PMID 39234565, 2024). "To identify potential TKS4-interacting molecules, we conducted a TKS4-IP-MS experiment, which demonstrated that CD2AP is among the TKS4 partner molecules in HCT116 colon cancer cells." (PMID 37894817, 2023). "The changes in the levels of TKS4 and CD2AP have interdependent regulatory effects on a partial EMT process in colon cancer cells." (PMID 37894817, 2023). "The CD2AP-Tks4 ratio drives the EMT process in colon cancer and HCT116 cells." (PMID 38985526, 2024). "Supporting this hypothesis, we previously identified CD2-associated protein (CD2AP) as a direct Tks4-interacting partner and demonstrated that Tks4 and CD2AP form a complex that potentially regulates an EMT-like process during colon cancer development." (PMID 38985526, 2024). "Low CD2AP expression has been associated with poor prognosis in gastric cancer and renal clear cell carcinoma patients, and its reduction in vitro triggers unfavorable partial EMT processes in colon cancer cells." (PMID 39234565, 2024). "The expression levels of CD2AP, GRB2, WASL, and CAPZA1 are generally downregulated, while those of SRC and CTTN are upregulated in colon cancer samples compared with their levels in normal samples at the RNA and/or protein levels." (PMID 39234565, 2024). "Our results showed that TKS4 and CD2AP form a scaffolding protein complex and that they can regulate migration and EMT-related pathways in HCT116 colon cancer cells." (PMID 37894817, 2023). "In this study we demonstrated that CD2AP can bind to TKS4 in vitro and that it co-localizes with TKS4 in HCT116 colon cancer cells." (PMID 37894817, 2023). "The results showed that the silencing of CD2AP and/or TKS4 increased colon cancer cell migration compared with the control cells." (PMID 37894817, 2023). "Another study revealed that CD2AP and TKS4 could form a scaffolding protein complex to regulate migration and EMT-related pathways in colon cancer cells." (PMID 40362690, 2025). "A recent study has reported that CD2AP/TKS4 complexes could regulate migration and EMT-related pathways in colon cancer cells." (PMID 40362690, 2025). "In addition, CD2AP was found to form a complex with the TKS4 protein to regulate migration and epithelial-mesenchymal transition pathways in colon cancer cells." (PMID 39353894, 2024). "Similarly, our results revealed that the interaction between CD2AP and TKS4 might have a role in tumor development, particularly in regulating a partial EMT state in colon cancer cells." (PMID 37894817, 2023). "The experimentally induced up and down regulation of the CD2AP and TKS4 expression levels revealed that they both might play a role in tumor development, notably in potentially regulating a partial-EMT state in HCT116 colon cancer cells." (PMID 37894817, 2023).
renal fibrosis (5 papers, 2020 to 2025). A final common manifestation of a wide variety of chronic kidney diseases characterized by glomerulosclerosis and tubulointerstitial fibrosis. "For example, in patients with renal fibrosis, urinary exosomal miR-200b is elevated, and the decrease in miR-29c and CD2AP mRNA is associated with renal function and fibrosis severity." (PMID 40332144, 2025). "Renal fibrosis is the hallmark of permanent damage in CKD and has been associated with higher levels of miR-200b and lower levels of miR-29c as well as CD2AP mRNA." (PMID 32849923, 2020). "The podocyte marker CD2AP was found to be downregulated in urinary exosomes from CKD patients (relative to healthy controls), and its levels were linked to the severity of renal fibrosis." (PMID 33371311, 2020).
amyloid (4 papers, 2022 to 2025). "In sum, there is evidence for a role for CD2AP in Aβ toxicity and pathology, but which cell types are reliant on CD2AP and how exactly CD2AP regulates Aβ biology in specific models of amyloidosis and AD remain to be fully investigated." (PMID 40462155, 2025). "In the APP/PS1 mouse model of amyloidosis, Xue and colleagues reported that neuronal knockout of CD2AP exacerbates tau hyperphosphorylation, synaptic impairments and cognitive deficits." (PMID 40462155, 2025). "On the one hand, CD2AP haploinsufficiency has limited impact on Aβ accumulation in the APP/PS1 mouse model of amyloidosis, raising some doubt as to whether endocytic Aβ production from brain cells is the defining role of CD2AP in AD." (PMID 40462155, 2025). "Together, these studies have suggested a role for CD2AP in amyloid pathogenesis." (PMID 35359443, 2022). "Hence, RIN3 may act as a scaffold between CD2AP and BIN1: promoting amyloid pathology via CD2AP and enhancing tau pathology via BIN1." (PMID 35359443, 2022).
congenital nephrotic syndrome (4 papers, 2007 to 2024). "In congenital nephrotic syndrome (NS) model caused by mutational defect in CD2AP, there were dilatation of the membrane of rough ER and increased number of cytoplasmic empty-appearing vacuoles, implying inadequate protein folding ERS." (PMID 26893923, 2015). "The gene mutated for congenital nephrotic syndrome, nephrin (NPHS1) is localized to the slit diaphragm of the podocyte and is tightly associated with CD2-associated protein (CD2AP)." (PMID 17647026, 2007). "Mice with CD2AP knockout develop congenital nephrotic syndrome, similar to congenital nephrotic syndrome of Finnish type." (PMID 17647026, 2007). "Likewise, CD2AP is a cytoplasmic podocyte protein found to play a role in congenital nephrotic syndrome in mice and some human FSGS." (PMID 34803506, 2021). "Moreover, mice lacking CD2AP exhibit a congenital nephrotic syndrome, indicating a role for CD2AP in kidneys development." (PMID 38388461, 2024).
diabetes (4 papers, 2016 to 2024). "Single-cell analysis of four different mouse kidney disease models (nephrotoxic serum nephritis, diabetes, doxorubicin toxicity, and CD2AP deficiency) showed cell type-specific and injury type-specific response in glomeruli." (PMID 34778322, 2021). "By characterizing glomerular cells in healthy mice and in four different disease models (nephrotoxic serum nephritis, diabetes, doxorubicin toxicity, and CD2AP deficiency), seven different cell clusters and new markers of mesangial cells were identified in the scRNA-seq of healthy glomeruli." (PMID 36685214, 2022).
asthma (3 papers, 2020 to 2024). "CD2AP is a significant risk factor for asthma, established during repeated GWAS." (PMID 39125683, 2024). "In the UKB cohort, CD33 variant rs3865444 had nominal association with asthma (p = 2.84 x 10−4), while CD2AP variant rs9349407 had nominal association with UC (p = 0.0004) and PICALM variant rs3851179 had nominal association with hay fever or allergic rhinitis (p = 4.42 x 10−4)." (PMID 33152005, 2020). "Additionally, I found that CD2AP, which is highly interacted with CD247 is highly correlated with moderate-to-severe asthma." (PMID 32512817, 2020).
Cognitive impairment (3 papers, 2024 to 2025). Abnormal cognition is characterized by deficits in thinking, reasoning, or remembering. "In recent years, a series of complementary works have clarified and deepened the role of CD2AP in AD neuropathology, cell signaling, cognitive impairment and brain vascular dysfunction using mice with loss and gain of CD2AP function in specific cell types." (PMID 40462155, 2025). "Our previous study revealed that the CD2AP risk allele (C allele of rs9296559) is correlated with increased CSF t-tau and p-tau levels in patients with mild cognitive impairment." (PMID 39696695, 2024). "The very large decrease (60%) in baseline red blood cell velocity (a proxy for CBF) and the 50% increase in capillary stalls found in the mutant CD2AP mice likely cause cognitive impairment in these mice based on studies reporting memory deficits in models with similar CBF abnormalities." (PMID 40462155, 2025). "As human studies found the strongest correlation between low levels of vascular CD2AP and cognitive impairment in male AD individuals, male mice were selected for all behavioral analyses." (PMID 40462155, 2025). "We conducted an analysis of two distinct cohorts and revealed a correlation between CD2AP rs9296559 and higher CSF total tau (t-tau) and phosphorylated tau (p-tau) levels in patients with mild cognitive impairment." (PMID 39696695, 2024). "A study of 73 non-demented and demented patients revealed that CD2AP polymorphism rs9349407 was associated with a 6% lower Mini-Mental State Examination score, a questionnaire used to measure cognitive impairment and screen for dementia." (PMID 40462155, 2025). "Taken together, these behavioral results indicated that neuron-specific Cd2ap depletion does not lead to cognitive impairment." (PMID 39696695, 2024). "Importantly, Nestin-cre driven conditional knockout for CD2AP that abrogates gene expression in neuronal progenitors and neurons, and neuron-specific CD2AP knockout mice show no signs of cognitive impairment, even at 12 and 15 months of age, respectively." (PMID 40462155, 2025).
lung carcinoma (3 papers, 2018 to 2025). "However, the specific role of CD2AP in malignancies, especially in lung cancers, has been less elucidated." (PMID 41425578, 2025). "We discovered that while Grb2 and cortactin are present to a lesser degree in the Tks4-formed complex, CD2AP and CAPZA1 are abundant in the tested three lung cancer cell lines." (PMID 38985526, 2024).
Nephropathy (3 papers, 2013 to 2025). A nonspecific term referring to disease or damage of the kidneys. "The link between AD and nephropathy caused by CD2AP genetic variants also remains a mystery." (PMID 40462155, 2025). "However, it did not significantly reduce the increased expression of fibronectin, further increased the expression of LEF1, upregulated PAI-1 (CD2AP−/−+tankyrase inhibitor), a fibrogenic factor that has been associated with the development of nephropathy, and increased pro-apoptotic signaling." (PMID 27441654, 2016). "Collectively, the data indicate that suppression of cd2ap coupled with inhibition of tankyrases leads to more severe kidney damage than knockdown of cd2ap alone and increases mortality of the larvae." (PMID 27441654, 2016). "Decreased expression of CD2AP was observed in a PAN-induced rat model of nephropathy, while increased expression of CD2AP was observed in an adriamycin-induced nephrotic (ADN) rat model." (PMID 23710442, 2013). "This comparison suggests that some cases of nephropathy and AD may converge mechanistically through CD2AP." (PMID 40462155, 2025). "However, inhibition of tankyrases in the absence of CD2AP enhances the expression of podocyte injury markers and aggravates kidney damage." (PMID 27441654, 2016).
renal clear cell carcinoma (3 papers, 2024 to 2025). "As for CD2AP, researchers have identified it as a diagnostic and prognostic biomarker for patients with renal clear cell carcinoma." (PMID 40362690, 2025). "Pan-cancer analysis of CD2AP revealed that its protein levels were evaluated in most types of cancers, except for clear cell renal cell carcinoma (CCRCC), head and neck squamous cell carcinomas (HNSCC), and lung squamous cell carcinoma (LSCC)." (PMID 41425578, 2025). "However, few studies have focused on the correlation between the expression and prognosis of CD2AP in renal clear cell carcinoma (ccRCC)." (PMID 38457255, 2024).
tauopathy (3 papers, 2021 to 2025). Neurodegenerative disorders involving deposition of abnormal tau protein isoforms (tau proteins) in neurons and glial cells in the brain. "The association of CD2AP neuronal expression was detected in 3 repeat‐tau‐diseases such as AD and Pick’s disease but not 4-repeat-tauopathies including progressive supranuclear palsy and corticobasal syndrome." (PMID 40462155, 2025). "AD-associated genetic variants CD2AP rs9381563 might affect the mechanisms involved both in brain tauopathy and neurodegeneration, and SLC24A4/RIN3 rs10498633 in brain amyloidosis and tauopathy." (PMID 33419465, 2021). "Thus, whether defects in CD2AP lead to the accumulation of tau and contribute to tauopathies warrants future studies." (PMID 40462155, 2025).
diabetic nephropathy (2 papers, 2013 to 2022). "Umbelliferone inhibits the expression of CD2AP and the activation of the TLR/NF-κB pathway, reducing the secretion of inflammatory factors in a rat model of diabetic nephropathy, thereby improving renal function." (PMID 36359915, 2022).
end-stage renal disease (2 papers, 2025). "In this context, a meta-analysis has linked CD2AP to end-stage renal disease in patients with type 1 diabetes." (PMID 40462155, 2025).
glioblastoma (2 papers, 2024 to 2025). The most malignant astrocytic tumor (WHO grade IV). "In glioblastoma, CD2AP promotes tumour progression through TRIM5-mediated NF-kB signalling." (PMID 41425578, 2025). "Although emerging evidence suggests that CD2AP is associated with several malignant tumors, there is no study investigating the expression and biological significance of CD2AP in glioblastoma multiforme (GBM)." (PMID 39353894, 2024).
kidney inflammation (2 papers, 2021 to 2022). "A previous study has showed CD2AP binds to intercellular adhesion molecule-1 to regulate mechanical signal transduction, leukocyte adhesion, and exerts an important role in kidney inflammation." (PMID 35172672, 2022).
nephrosis (2 papers, 2004 to 2017). Pathological processes of the KIDNEY without inflammatory or neoplastic components. "Double immunofluorescence staining for nephrin and CD2AP or SHIP2 revealed that the expression of CD2AP appears diminished and SHIP2 increased in podocytes in rats with PA-induced nephrosis, confirming the data obtained in cultured cells." (PMID 28878342, 2017). "To define whether PA-treatment leads to downregulation of CD2AP and upregulation of SHIP2 in vivo, we immunostained kidneys of rats with PA-induced nephrosis." (PMID 28878342, 2017). "Mice lacking slit-diaphragm proteins CD2AP and Neph-1 similarly present with very early-onset nephrosis." (PMID 15208719, 2004).
Parkinson disease (2 papers, 2020 to 2025). A progressive degenerative disorder of the central nervous system characterized by loss of dopamine producing neurons in the substantia nigra and the presence of Lewy bodies in the substantia nigra and locus coeruleus. "In contrast, the pathways in the CD2AP low-expressed group were mainly related to hematopoietic cells, oxidative phosphorylation, Parkinson’s disease, the ribosome, and systemic lupus erythematosus." (PMID 41425578, 2025).
Stroke (2 papers, 2019 to 2021). Sudden impairment of blood flow to a part of the brain due to occlusion or rupture of an artery to the brain. "Further, the variant near CD2AP gene associates with the development and maintenance of the blood-brain barrier, a specialized vascular structure of the central nervous system which, when disrupted, has been linked with epilepsy, stroke and AD." (PMID 34992629, 2021).
acute coronary syndrome (1 paper, 2024). Signs and symptoms related to acute ischemia of the myocardium secondary to coronary artery disease. "Compared with the acute coronary syndrome (ACS), CD2AP and DSTN were higher expressed in monocytes cell of stable angina pectoris (SAP), and RPN1 was higher expressed in B cell of SAP." (PMID 39666769, 2024).